LCA5L (lebercilin LCA5 like)
Synonyms: C21orf13; MGC33295
Tractability: PROTAC: ubiquitination databases record sites on it.
Gene: Protein-coding gene on chromosome 21 (39,405,135 to 39,445,805, reverse strand). Ensembl gene ENSG00000157578.
Subcellular location (Human Protein Atlas): Flagellar centriole; Mid piece; Nuclear speckles; Nucleoplasm; Cytosol; End piece; Principal piece
Gene Ontology:
Molecular function: protein binding
Biological process: intraciliary transport
Cellular component: axoneme
Genetic constraint (gnomAD): Loss-of-function variants: 19 observed, 25.31 expected, observed/expected ratio (o/e) 0.75, 90% interval 0.52 to 1.1. The upper end of that interval is the gene's LOEUF score, 1.1, which puts it in group 4 of 6, group 1 being the genes least tolerant of losing a copy. Missense variants: 494 observed, 582.97 expected, observed/expected ratio (o/e) 0.85, 90% interval 0.79 to 0.91. Synonymous variants: 175 observed, 207.55 expected, observed/expected ratio (o/e) 0.84, 90% interval 0.75 to 0.96.
Homologues: Orthologues: chimpanzee LCA5L (98% identical), macaque LCA5L (96% identical), dog LCA5L (69% identical), rabbit LCA5L (67% identical), pig LCA5L (64% identical), rat Lca5l (62% identical), mouse Lca5l (62% identical), guinea pig LCA5L (59% identical), Drosophila melanogaster CG6652 (15% identical). Paralogues in human: LCA5 (25% identical).
Diseases named in the same sentence as LCA5L in open-access papers:
LCA5L is named in the same sentence as 2 diseases in open-access papers, as found by Europe PMC text mining. Sharing a sentence is not in itself a finding about the gene and the disease. The quoted sentences say what the papers report.
congenital heart defects (1 paper, 2018). "Although no direct evidence revealed the specific contribution of LCA5L in patients with DS, a study on the congenital heart defects confirmed that copy number variation of LCA5L also participated in the pathogenesis of congenital heart defects." (PMID 29649131, 2018).
LCA5L also shares sentences with these, for which no sentence is quoted: synucleinopathy (1 paper).